ENSG00000201384
Gene: Small nucleolar RNA gene on chromosome 14 (77,201,026 to 77,201,140, reverse strand). Ensembl gene ENSG00000201384.
Homologues: Orthologues: rat LOC120095737 (70% identical), rat Snora32 (64% identical), rat LOC120097588 (61% identical), mouse Gm54781 (60% identical), rat LOC120102640 (51% identical), rat LOC120100386 (46% identical), rat LOC120098685 (44% identical). Paralogues in human: SNORA32 (76% identical).